MEFV (MEFV innate immunity regulator, pyrin)
Diseases named in the same sentence as MEFV in open-access papers (continued):
Sharing a sentence is not in itself a finding about the gene and the disease.
lupus nephritis (1 paper, 2025). Glomerulonephritis in the context of systemic lupus erythematosus. "In summary, the E148Q variant of the MEFV gene may protect patients with lupus nephritis by modulating immune responses and shifting the balance from adaptive to innate immunity." (PMID 40692783, 2025). "This shift from adaptive to innate immunity, mediated by MEFV variants such as E148Q, may reduce the severity of lupus nephritis by reducing autoantibody production." (PMID 40692783, 2025). "The number of MEFV variants in patients with lupus nephritis was significantly lower than the number of MEFV variants in patients without lupus nephritis (Mean ± SD; 0.80 ± 0.87 vs. 1.53 ± 0.94, = 0.006, not shown)." (PMID 40692783, 2025).
migraine (1 paper, 2021). "This is consistent with the emerging role for inflammasomes in migraine and the association of MEFV variants with the risk of migraine." (PMID 35126383, 2021).
myasthenia gravis (1 paper, 2016). Myasthenia gravis (MG) is a rare, clinically heterogeneous, autoimmune disorder of the neuromuscular junction characterized by fatigable weakness of voluntary muscles. "We report the first case of Morvan’s syndrome (MoS) and myasthenia gravis (MG) related to FMF harboring MEFV mutations (L110P/E148Q)." (PMID 27026266, 2016).
myelofibrosis (1 paper, 2015). A partial or complete replacement of the bone marrow stroma by fibrous tissue. "A somatic, myeloid restricted mutation in the Mediterranean fever gene of a patient with post-PV myelofibrosis expanded from negligible to 46 % of total MEFV alleles in peripheral blood cells, parallel to the development of colchicine responsive inflammatory fever bouts." (PMID 26123310, 2015).
non-bacterial osteomyelitis (1 paper, 2022). "Studies related to chronic non-bacterial osteomyelitis indicated that the frequency of MEFV gene mutations increased in the disease, and the disease phenotype was more severe in patients with MEFV gene mutations." (PMID 35909123, 2022).
PASH syndrome (1 paper, 2025). "This case report describes a PASH syndrome patient with the MEFV variant (NM_000243.3.442G > C; p.Glu148Gln)." (PMID 40861239, 2025). "Studies have demonstrated elevated MEFV variant rates in patients with complex HS (including PASH syndrome), potentially playing an important role in autoinflammatory pathogenesis." (PMID 40861239, 2025). "This study reports a challenging case of PASH syndrome in which whole exome sequencing detected the MEFV gene variant (p.E148Q)." (PMID 40861239, 2025). "PASH syndrome is considered a polygenic autoinflammatory disease associated with multiple gene variants, among which MEFV variants may play a significant role." (PMID 40861239, 2025).
polyarthritis (1 paper, 2023). "In this study, no statistical difference was found among monoarthritis, polyarthritis, and polyarthralgia groups with MEFV gene mutations and high ASO levels." (PMID 37671203, 2023).
psoriasis (1 paper, 2025). An autoimmune condition characterized by red, well-delineated plaques with silvery scales that are usually on the extensor surfaces and scalp. "IL-1β, NLRC4, MEFV, and CASP have been reported as inflammasomes associated with psoriasis." (PMID 40861543, 2025).
renal calculi (1 paper, 2023). "The methylation% of the MEFV exon 2 in FMF patients with renal calculi was significantly higher than those without renal calculi." (PMID 36661534, 2023).
spondylitis (1 paper, 2025). The inflammation of a vertebra. "In FMF-associated spondylitis, there is limited available data regarding the influence of MEFV mutations on clinical symptoms." (PMID 41137223, 2025).
tendinitis (1 paper, 2024). Inflammation of a tendon, usually resulting from an overuse injury. "Our analysis revealed a distinct expression profile of inflammasome-related genes in tendinitis, with NLRP6, NLRP1, and MEFV showing significant correlations with immune checkpoint molecules." (PMID 38919626, 2024).
ulcers (1 paper, 2023). "Immunohistochemical analysis and in situ hybridization with interleukin-1β (IL-1β) showed a high expression of IL-1β only in injured areas, suggesting that IL-1β may be involved in the formation of ulcers in patients with intestinal BD carrying MEFV gene mutations." (PMID 37176572, 2023).
vesicoureteral reflux (1 paper, 2015). Abnormal flow of urine from the urinary bladder back into the ureters. "There is a possibility that control of inflammation caused by the surgery for vesicoureteral reflux in the local site didn’t work well on the background of heterozygous mutation of MEFV gene, and as a result, nephrogenic adenoma appeared." (PMID 26428868, 2015).
Yersinia infection (1 paper, 2020). "Interestingly, studies on FMF showed that pyrin mutations cause a resistance to Yersinia infection, suggesting that individuals with MEFV mutations could have been selected during the plague pandemics." (PMID 33490003, 2020).
infection (14 papers, 2016 to 2025). The state of being infected such as from the introduction of a foreign agent such as serum, vaccine, antigenic substance or organism. "Because the pyrin variants that cause FMF lead to the excessive activation of the inflammasome, due to gain-of-function mutations in the MEFV gene, this excessive activation compensates for the inhibitory role of YopM that enables cellular pyroptosis, resulting in resistance to infection." (PMID 34946123, 2021). "Results show that several rare pathogenic/likely pathogenic genomic variants in genes CFTR, MASP2, MEFV, TNFRSF13B, and RNASEL likely contribute to the severe infection outcomes in our patient cohort." (PMID 39062917, 2024). "These variants were found in inflammasome genes (NLRP1/3 and CASP1), genes mediating inflammasome inactivation via auto- and mitophagy (RIPK2 and MEFV), and genes involved in the response to infection with DNA viruses (POLR3A, DHX58, and IFIH1) and type-1 interferons (TYK2 and PTPRC)." (PMID 37626706, 2023). "MEFV (OMIM: 608107) encodes pyrin whose function as an innate immune sensor can trigger inflammasome formation, allowing the production of inflammatory mediators during infection." (PMID 33499153, 2021). "These variants were found in inflammasome genes (NLRP1/3, CASP1), genes mediating inflammasome inactivation via auto and mitophagy (RIPK2, MEFV), and genes involved in response to infection with DNA viruses (POLR3A, DHX58, IFIH1) and to type-1 interferons (TYK2, PTPRC)." (PMID 31235738, 2019). "In contrast, other inflammasome sensors, such as NLRC4, AIM2, and MEFV (a human gene involved in making pyrin that has a role in inflammation and infection), do not respond to nigericin." (PMID 40305196, 2025). "MEFV has previously been shown to be up-regulated in human monocytes and Mø in response to Burkholderia cenocepacia infection and plays an important role in regulating IL1B release during infection." (PMID 27000047, 2016).
tumor (7 papers, 2020 to 2023). "Patients with TNFRSF1A variants (n = 8; 100%) also showed significant more often skin rashes compared to patients with MEFV variants (n = 4; 21%, p = 0.0074)." (PMID 32563262, 2020).
genetic disorder (5 papers, 2013 to 2025). "FMF is a genetic disease caused by mutations in the MEFV (MEditerranean FeVer) gene, which is present on the short arm of chromosome 16 (16p13.3) and is made of 10 exons." (PMID 38409042, 2024).
autosomal recessive disease (4 papers, 2012 to 2025). Autosomal recessive form of disease. "FMF is an autosomal recessive disease caused by mutations in the MEFV (MEditerranean FeVer) gene, which is located on the short arm of chromosome 16 (16p13.3)." (PMID 41472723, 2025). "FMF is considered as an autosomal recessive hereditary disease, associated with a single gene named MEFV." (PMID 23206577, 2012). "FMF is considered an autosomal-recessive inherited disease caused by mutations in the MEFV gene." (PMID 37176572, 2023).
cancer (4 papers, 2014 to 2025). A tumor composed of atypical neoplastic, often pleomorphic cells that invade other tissues. "MEFV gene mutations observed in familial Mediterranean fever patients who have developed the two more frequent cancers and the other malignant neoplasms in the current FMF cohort." (PMID 38799474, 2024). "SS has also been linked to cancer therapies, specific antibiotics, and MEFV gene mutations." (PMID 40869568, 2025). "Based on the current data, it may be hypothesized that the MEFV gene is a cancer susceptibility gene." (PMID 25202401, 2014). "Based on the current data, it is hypothesized that the MEFV gene is a cancer susceptibility gene." (PMID 25202401, 2014). "It has been reported that most of the 8 ARGs (VIM, UFM1, TSC2, SRC, MEFV, CTTN, CFTR and CDKN1A) are related to cancer." (PMID 35121801, 2022).
bacterial infections (2 papers, 2022 to 2024). "Pyrin is encoded by the MEFV gene and a sensor of bacterial infections, such as Yersinia pestis." (PMID 35655291, 2022). "Pyrin, encoded by MEFV gene, is a cytosolic PRR that forms an inflammasome complex in response to bacterial infections." (PMID 39201704, 2024).
inflammation (2 papers, 2019 to 2021). Aberrant reaction of the microcirculation characterized by movement of fluid and leukocytes from the blood into extravascular tissues. "Pyrin-associated auto-inflammation with neutrophilic dermatosis (PAAND) is due to mutations in the MEFV gene." (PMID 34201078, 2021). "Large cohort studies including other diseases manifesting neurological inflammation are warranted to clarify the relationship between MEFV gene mutations and neurological inflammatory diseases." (PMID 31682063, 2019). "Patients with CNS inflammation and symptoms related to NBD or NSD frequently exhibited MEFV gene mutations." (PMID 31682063, 2019).
hematological neoplasms (1 paper, 2024). "This aligned with what was previously studied regarding the identification of a high frequency of MEFV gene mutations in patients with hematological neoplasms." (PMID 38799474, 2024).
MEFV also shares sentences with these, for which no sentence is quoted: ulcerative colitis (5 papers); erysipelas (4); sacroiliitis (4); fibromyalgia (3); Myalgia (3); polyarteritis nodosa (3); colon cancer (2); colorectal cancer (2); complement deficiencies (2); endothelial dysfunction (2); gout (2); periodontitis (2); primary immunodeficiencies (2); tuberculosis (2); 22q11.2 deletion syndrome (1); adenitis (1); atherosclerosis (1); atopic dermatitis (1); autosomal dominant disease (1); Blau syndrome (1); CANDLE) syndrome (1); cannabis dependence (1); Cardiovascular Disease (1); chronic infantile neurologic cutaneous articular syndrome (1); chronic myelomonocytic leukemia (1); Cyclic neutropenia (1); demyelination (1); Dent Disease 2 (1); Dowling-Degos disease (1); dyslipidemia (1).
A further 58 diseases each share a sentence with MEFV in 1 paper.